Y_RNA (Y RNA )
Gene: Miscellaneous RNA gene on chromosome 2 (170,783,167 to 170,783,271, forward strand). Ensembl gene ENSG00000222509.
Homologues: Orthologues: chimpanzee Y_RNA (99% identical), macaque Y_RNA (96% identical). Paralogues in human: RNY1P11 (84% identical), Y_RNA (83% identical), RNY1 (82% identical), Y_RNA (82% identical), Y_RNA (81% identical), Y_RNA (80% identical), Y_RNA (79% identical), RNY1P12 (78% identical), Y_RNA (78% identical), Y_RNA (77% identical), RNY1P10 (76% identical), RNY1P15 (76% identical), and 91 more.